ENSG00000287286 (novel transcript, antisense to RUBCN)
Gene: Long non-coding RNA gene on chromosome 3 (197,665,316 to 197,674,863, forward strand). Ensembl gene ENSG00000287286.
Gene Ontology:
Biological process: miRNA-mediated post-transcriptional gene silencing
Cellular component: RISC complex